BTLA (B and T lymphocyte associated)
Diseases named in the same sentence as BTLA in open-access papers (continued):
Sharing a sentence is not in itself a finding about the gene and the disease.
systemic lupus erythematosus (continued). "In the view of developing new therapeutic strategies for SLE, identifying molecular and/or cellular elements leading to enhanced BTLA expression on lupus aTregs is an open avenue." (PMID 34899718, 2021). "The aim of this study was to investigate the expression of BTLA on T-cells and its role on the effector cell function of Th1, Th2, and Th17 cells in patients with systemic lupus erythematosus." (PMID 31514450, 2019). "BTLA seems to be an important co-inhibitory molecule in the T-cell homeostasis of patients with systemic lupus erythematosus and crucial for disease activity." (PMID 31514450, 2019). "Although peripheral B cells express a very high amount of BTLA, previous works in the context of autoimmunity mainly focused on T cells, and whether BTLA expression on B cells plays a role in the lupus pathogenesis is still unclear." (PMID 39768154, 2024). "These cells display an activated and antibody-secreting cell phenotype, and we propose that their low BTLA expression may favor their expansion and rapid differentiation into plasmablasts in lupus patients." (PMID 39768154, 2024). "Although peripheral B cells express very high BTLA levels, previous work concerning BTLA expression in the context of autoimmunity mainly focused on T cells, and whether BTLA expression on B cells plays a role in lupus pathogenesis is still unclear." (PMID 39768154, 2024). "To investigate whether enhanced BTLA expression by lupus aTregs may have biological significance in the disease pathogenesis, we further focused on pathogenic effector T cells." (PMID 34899718, 2021). "However, we did not evidence any enhancement of sHVEM in lupus patients compared to HC (unpublished results), nor any correlation between sHVEM in lupus sera and the higher level of BTLA expression by lupus a Tregs." (PMID 34899718, 2021). "In the present work, we evidenced that ex vivo lupus Tregs express higher levels of BTLA." (PMID 34899718, 2021). "What are the potential consequences of such a higher BTLA expression by lupus aTregs?" (PMID 34899718, 2021). "Interestingly, we have previously shown that BTLA expression is significantly diminished in lupus CD4+ T cells compared to HC following in vitro TCR activation." (PMID 34899718, 2021). "As Treg-mediated suppression was described to be defective in SLE patients, understanding whether defective BTLA expression could influence the function of lupus Tregs would be particularly interesting." (PMID 34899718, 2021). "Further studies are required to define whether miR155 (and/or others) effectively targets BTLA in human and whether a dysregulated miRNA expression by lupus aTregs may account for enhanced BTLA expression." (PMID 34899718, 2021). "We recently demonstrated that the BTLA pathway is altered in CD4+ T cells from lupus patients." (PMID 34899718, 2021). "Altogether, our data suggest that the altered BTLA expression by lupus Tregs and effector T cells may contribute to decreased numbers of Tregs and potentially to their reduced-suppressive activity." (PMID 34899718, 2021). "Our results suggest that the higher BTLA expression on the surface of lupus aTregs may account for the reduced frequency of this Treg subset in lupus patients." (PMID 34899718, 2021). "We evidenced a higher expression of the co-inhibitory receptor BTLA in lupus aTregs, and our results support the hypothesis of a link between this observation and the diminution of aTreg frequency in lupus settings." (PMID 34899718, 2021). "In the present work, we performed an in-depth analysis of BTLA expression on CD4+ T cell subsets suspected to play a key role in lupus pathogenesis, either by promoting the Ab-response or by limiting lymphocyte activation, i.e. cTFH cells and Tregs respectively." (PMID 34899718, 2021).
systemic lupus erythematosus (continued). "Finally, we observed that the HVEM/BTLA ratio is significantly lower in Tregs from lupus patients compared to healthy controls, whereas ex vivo effector CD4+ T cells express higher BTLA levels." (PMID 34899718, 2021). "Very interestingly, we observed an altered expression of BTLA on lupus Treg subsets." (PMID 34899718, 2021). "BTLA expression by lupus Tregs was recently explored by two groups." (PMID 34899718, 2021). "The reduced BTLA expression on DN B cells logically inversely correlates with BTLAlow DN B cell frequency, suggesting that BTLA downregulation could favor B cell proliferation and increased numbers of this particular B cell subset in lupus settings (p < 0.0001)." (PMID 39768154, 2024). "Surprisingly, and contrary to what was observed in in vitro stimulated T cells, we noticed that ex vivo CD4+ effector T cells from lupus patients express higher levels of BTLA than those from HC, suggesting that lupus Teffs may be efficiently suppressed in vivo." (PMID 34899718, 2021). "Prior studies reported defective function of BTLA by T cells in patients with systemic lupus erythematosus (SLE), whereas nothing is known about its role on B cells in SLE, a disease with various B cell abnormalities." (PMID 33968071, 2021). "Indeed, BTLA expression was significantly increased on terminally differentiated and highly suppressive aTregs, but not on rTregs (Tregs in a quiescent state that can differentiate into aTregs upon stimulation), of lupus patients compared to HC." (PMID 34899718, 2021). "In the present study, we examine the expression of BTLA, as well as that of its ligand HVEM, on various B cell subsets in lupus patients compared to HCs." (PMID 39768154, 2024). "In the present study, we examine the expression of BTLA, as well as its ligand HVEM (Herpesvirus Entry Mediator), on various B cell subsets in lupus patients compared to healthy controls (HCs)." (PMID 39768154, 2024). "In this study, we found that ex vivo expression of BTLA on CD4+ T cells (both naive and memory) and on cTFH was comparable between lupus patients and healthy individuals." (PMID 34899718, 2021). "In a murine lupus model, CD4+ and CD8+ T-cells from BTLA−/− MRL-lpr/lpr mice showed enhanced responses in α-CD3-induced proliferation as compared to BTLA+/+ MRL-lpr/lpr mice." (PMID 31514450, 2019). "Our data suggest that an altered expression of BTLA and HVEM could be involved in an impaired regulation of autoreactive T cells in lupus." (PMID 34899718, 2021). "However, lupus CD11c+Tbet+ DN memory B cells do not seem to display altered BTLA expression compared to HCs." (PMID 39768154, 2024). "Interestingly, we did not observe any association between disease activity or the presence of anti-dsDNA and the level of BTLA expression in rTregs, which did not display increased BTLA expression in lupus patients compared to HC." (PMID 34899718, 2021). "Finally, BTLA expression is not significantly higher on aTregs from patients harboring proteinuria compared to lupus patients with no proteinuria; however, the number of proteinuria positive patients in our cohort is low (n=8)." (PMID 34899718, 2021). "However, our previous study revealed that despite normal levels of BTLA expression, CD4+ T cells from lupus patients display an altered functionality of the BTLA signaling pathway, and may thus consequently be refractory to Treg-mediated suppression." (PMID 34899718, 2021). "Importantly, higher BTLA expression on lupus aTreg was not related to the age or to the treatments received by lupus patients." (PMID 34899718, 2021). "However, we interestingly observed that BTLA expression is significantly increased on activated Tregs, but not resting Tregs, from lupus patients, especially those displaying an active disease." (PMID 34899718, 2021). "In patients with active systemic lupus erythematosus (SLE), the proportion of CD4+BTLA+ T cells is markedly decreased." (PMID 33859648, 2021).
systemic lupus erythematosus (continued). "Whether sHVEM directly influences BTLA expression is not known but we wondered whether there is a link between BTLA expression and sHVEM levels in our lupus cohort." (PMID 34899718, 2021). "Our data support this hypothesis, as BTLA expression by lupus aTregs strongly correlates with decreased frequencies of aTregs in PBMCs from lupus patients and we propose a model in which HVEM-expressing Tregs mediate BTLA-expressing Tregs inhibition through trans-interaction." (PMID 34899718, 2021). "BTLA, the inhibitory binding partner of HVEM, was maintained at normal levels in lupus T cells (data not shown)." (PMID 39688922, 2024). "We did not detect significant ex vivo variations of BTLA expression on total CD4+ T cells (naive and memory), cTFH or TFH subsets between lupus patients and healthy controls." (PMID 34899718, 2021). "Moreover, we showed that the induction of the BTLA pathway does not properly suppress CD4+ T cell activation and proliferation in lupus patients compared to healthy controls (HCs)." (PMID 39768154, 2024).
Autoimmunity (13 papers, 2011 to 2025). The occurrence of an immune reaction against the organism's own cells or tissues. "In mice, BTLA deficiency is associated with hyper-reactive B and T cells and enhanced susceptibility to autoimmunity, which indicates its role as a checkpoint receptor." (PMID 34885092, 2021). "A murine autoimmune diabetes model has shown that mice transferred with BTLA−/− OT-I cell showed aggressive insulitis and infiltration of islets suggesting that BTLA is required for regulation of CD8+ associated autoimmunity." (PMID 31514450, 2019). "In this study, we show that BTLA is an RA-susceptibility gene and provide evidence that BTLA is involved in the protection from autoimmunity in humans." (PMID 21403914, 2011). "By removing BTLA-mediated suppression, elevated T cell activation may lead to off-target tissue damage, particularly in organs susceptible to autoimmunity such as the skin, gut, liver, lungs, and endocrine glands." (PMID 41471273, 2025). "The agents regulating the signals through coinhibitory molecules including CTLA-4, PD-1, and BTLA have the potential to regulate autoimmunity and responses to tumors and chronic infections." (PMID 22997525, 2012). "The effect of combined treatment with anti-BTLA mAb and anti-PD-1 mAb on autoimmunity has also been examined in NOD mice." (PMID 22997525, 2012). "Conversely, in certain pathological contexts where BTLA exerts protective roles, BTLA agonists could be developed to enhance immune tolerance, such as in transplantation or autoimmune disorders—highlighting the versatility of BTLA modulation." (PMID 41471273, 2025). "Given BTLA’s role as a co-inhibitory receptor, its blockade may similarly unleash autoimmunity and systemic inflammation." (PMID 41471273, 2025). "BTLA is suggested to play a vital role in the protection from autoimmunity." (PMID 33859648, 2021). "BTLA-deficient T and B cells show enhanced proliferation in response to anti-CD3 and anti-IgM stimulation, respectively, while BTLA-deficient mice exhibit enhanced predisposition to autoimmunity." (PMID 32775467, 2020). "Some studies have indicated HVEM/CD160/BTLA/LIGHT pathway may has an important role in the etiology of autoimmunity." (PMID 30842773, 2019). "However, given BTLA’s role in maintaining immune homeostasis, systemic blockade may carry risks of hyperinflammation or autoimmunity, highlighting the need for selective targeting strategies—such as bispecific antibodies that preferentially block BTLA in the TME or cell-specific delivery systems." (PMID 41471273, 2025). "Anti-BTLA mAb treatment can delay the onset of autoimmune diabetes in non-obese diabetic (NOD) mice, increase the proportion of Tregs, and direct the cytokine milieu away from autoimmunity." (PMID 33859648, 2021). "Obtaining a deeper mechanistic understanding of the signaling mechanisms by which DCs control T cell responses, such as the BTLA-HVEM-CD5 axis described here, is necessary for the development of new immunotherapies for the treatment of cancer, autoimmunity, and infection." (PMID 31191536, 2019).
colorectal cancer (12 papers, 2016 to 2025). A primary or metastatic malignant neoplasm that affects the colon or rectum. "In colorectal cancer, BTLA was significantly upregulated, which was associated with advanced tumor stage and a shorter survival time." (PMID 40243455, 2025). "From public databases, a significant favorable overall survival associated with high BTLA expression is observed in lung cancer, hepatocellular carcinoma, and colorectal cancer." (PMID 41471273, 2025). "In colorectal cancer, high BTLA expression has been linked to microsatellite-stable (MSS) tumors, which are less responsive to immune checkpoint inhibitors, further supporting its role as a marker of immune exclusion." (PMID 41471273, 2025). "Conversely, low expression of BTLA was associated with poor overall survival in patients with colorectal cancer." (PMID 34948416, 2021). "In colorectal cancer, BTLA expression is often elevated in MSS tumors, which tend to exhibit lower immunogenicity and greater resistance to immune checkpoint inhibitors." (PMID 41471273, 2025). "In addition, decreased BTLA levels predicted poor OS in colorectal cancers." (PMID 36467089, 2022). "However, the role of BTLA in prognosis and immunotherapy of colorectal cancer (CRC) remains unclear." (PMID 32793631, 2020). "Currently, a humanized anti-BTLA (JS004) designed to target HVEM/BTLA is undergoing a clinical trial of phase I for advanced solid tumors, including gastric adenocarcinoma, esophageal squamous cell carcinoma, liver, cervical, and MSI-H colorectal cancers." (PMID 40985894, 2025).
hepatocellular carcinoma (12 papers, 2018 to 2025). A malignant tumor that arises from hepatocytes. "In several cancer models, including hepatocellular carcinoma and gastric cancer, tumor-infiltrating NK cells exhibit elevated BTLA expression compared to peripheral NK cells from healthy controls." (PMID 41471273, 2025). "Clinical studies have shown that elevated BTLA expression on circulating or tumor-infiltrating B cells correlates with poor prognosis in several cancers, including hepatocellular carcinoma and non-small cell lung cancer." (PMID 41471273, 2025). "Similar co-expression patterns have been observed in hepatocellular carcinoma (HCC), where high BTLA levels were associated with advanced disease stage and a lower density of cytotoxic lymphocytes in the TME." (PMID 41471273, 2025). "BTLA increases more significantly in circulating CD4+ T cells than in CD8+ T cells in hepatocellular carcinoma (HCC)." (PMID 38785930, 2024). "In hepatocellular carcinoma, blockade of the BTLA-HVEM pathway increases lymphocyte IFN-γ production, suggesting that BTLA inhibits the antitumor response." (PMID 40574024, 2025). "BTLA expression is significantly upregulated on circulating and tumor-infiltrating CD4+ T cells in hepatocellular carcinoma." (PMID 40463377, 2025). "In the current study, we showed distinct changes of BTLA and HVEM expressions on peripheral blood CD4+ and CD8+ T cells in patients with hepatocellular carcinoma (HCC); BTLA expression were significantly upregulated on circulating CD4+ but not CD8+ T cells." (PMID 30116751, 2018). "In hepatocellular carcinoma (HCC) cases, the expression level of BTLA markedly increases in circulating CD4+ cells rather than in CD8+ T cells." (PMID 33859648, 2021).
lymphoma (12 papers, 2019 to 2024). A malignant (clonal) proliferation of B- lymphocytes or T- lymphocytes which involves the lymph nodes, bone marrow and/or extranodal sites. "Moreover, since it prevents the growth of aggressive Myc+Bcl2+ murine lymphoma cells that express BTLA and lack HVEM in vivo, CAR-T cells that restore loss of HVEM are a promising therapeutic strategy." (PMID 34069564, 2021). "Vδ2T cells highly express BTLA in the lymph nodes of lymphoma patients, and the circulating soluble BTLA (sBTLA) level can be used as an independent prognostic factor for the OS of patients after ICI treatment." (PMID 36793048, 2023). "It is involved in lymphomagenesis since its inactivating mutations lead to increased B-cell receptor dependent signaling and, via its ligand BTLA, to disrupted interaction of lymphoma B-cells with modulatory T-helper cells, thus linking lymphomagenesis to disrupted immune cell crosstalk." (PMID 34494161, 2022). "Furthermore, soluble HVEM inhibited the B-cell receptor signals via Syk and the B cell linker, and ERK phosphorylation in primary human FL B cells and in DoHH2 human lymphoma cells derived from tFL that expressed BTLA and carried a homozygous HVEM deletion." (PMID 34069564, 2021). "It has been reported that an impairment of BTLA expression in normal and lymphoma B cells may lead to cell-autonomous BCR activation and induce B cell growth, as a loss of BTLA dampers the threshold for cell activation." (PMID 32775467, 2020). "γδT cells need TCR signals to maintain their stability, and it has been suggested that the interaction between BTLA and HVEM inhibits the proliferation of Vγ9VδT cells and their response to lymphoma cells." (PMID 36793048, 2023). "Our work confirmed that BTLA regulates cell growth by the activation of ERK1/2, which transduces signaling depending on its ligand HVEM, a similar result observed in lymphoma." (PMID 36552785, 2022). "Further studies on lymphoma cells indicated that the BTLA-HVEM pathway participates in the differentiation and inhibition of γδ T cells after exposure to lymphoma cells, suggesting its involvement in lymphomagenesis." (PMID 32775467, 2020).
COVID-19 (11 papers, 2020 to 2024). A disease caused by infection with severe acute respiratory syndrome coronavirus 2. "In COVID-19 patients, the BTLA was significantly elevated on peripheral blood CD4+ and CD8+ T cells, when compared to the normal group." (PMID 35432324, 2022). "Strong signals among CD4+T cells, memory B cells, and monocytes in stage A indicate activation of BTLA in T and B cells in the early phase, which was in concordance with a previous report that severe COVID-19 expressed higher BTLA." (PMID 35095832, 2021). "Next, we examined the expression of the inhibitory receptors PD1, TIGIT, LAG-3, TIM-3, and BTLA of T cells in COVID-19 and malaria compared to healthy controls." (PMID 32983106, 2020). "We observed a significantly higher expression of BTLA on TM and EM CD8+ T cells in COVID-19 and malaria patients compared to healthy donors." (PMID 32983106, 2020). "BTLA is strongly upregulated in both CD4+ and CD8+ T cells from COVID-19 patients." (PMID 33859648, 2021). "To see whether similar effects can be observed in COVID-19, we assessed the frequencies of the co-inhibitory receptors PD1, TIGIT, BTLA, LAG-3, and TIM-3 on CD8+ and CD4+ T cells in COVID-19 and malaria patients and compared them with healthy individuals." (PMID 32983106, 2020). "Indeed, a lower BTLA frequency in memory compared to naive subsets of CD8+ and CD4+ T cells could be detected in COVID-19 and malaria patients as well as healthy donors." (PMID 32983106, 2020). "However, the decrease of BTLA on CD8+ T cell subsets detected in both, COVID-19 and malaria, was not as strong as in healthy subjects." (PMID 32983106, 2020).